DROSHA (drosha ribonuclease III)
Diseases named in the same sentence as DROSHA in open-access papers (continued):
Sharing a sentence is not in itself a finding about the gene and the disease.
cervical carcinoma (8 papers, 2013 to 2023). A carcinoma arising from either the exocervical squamous epithelium or the endocervical glandular epithelium. "The upregulation of miR-21 in cervical cancer was observed in association with the dysregulation of DROSHA, an important enzyme in the miRNA biogenesis pathway, and it is suggested to be modulated by HPV16 E6/E721,32." (PMID 33990639, 2021). "Expression of high-risk HPV E6 and E7 in HPV-negative C33A cervical carcinoma cells and primary human epithelial cells causes increased expression of DROSHA and DICER, and many DROSHA-regulated miRNAs are dysregulated in high-risk HPV16 E6/E7 expressing cells." (PMID 28862667, 2017). "Previous research indicated that HPV-positive cervical carcinoma cell lines exhibit higher levels of DROSHA and DICER mRNA compared to HPV-negative cervical carcinoma cell lines, suggesting dysregulation of DDR-related miRNA levels." (PMID 37735483, 2023). "For example, increased DICER1 and DROSHA mRNA expression were found in some human papillomavirus (HPV) positive cervical cancer cell lines." (PMID 37243263, 2023). "When comparing HPV+ve and −ve cervical carcinoma cell lines, higher levels of DROSHA and DICER mRNA were observed in HPV+ve cancer lines." (PMID 35806128, 2022). "Murty’s group found an increase in the chromosome 5p copy number in invasive cervical cancer, which results in the overexpression of a number of its target genes, including DROSHA." (PMID 35806128, 2022). "Chromosome 5p amplifications are found in some cervical carcinomas, and DROSHA is the most significantly overexpressed transcript in cervical tumors with 5p gain." (PMID 28862667, 2017). "Indeed, copy number gain in chromosome 5p, where DROSHA is located, was a frequent observation in cervical cancer." (PMID 35806128, 2022). "Similarly, increased expression of DROSHA related to a copy number gain was described before in cervical cancer and was shown to result in altered miRNA expression profiles." (PMID 26993771, 2016). "However, the precise stage of cervical cancer progression where DROSHA expression increased remains unclear." (PMID 35806128, 2022). "The mRNA and protein expression of DROSHA and DICER increased when ectopic hrHPV E6/E7 were expressed in the normal human epithelial cells and C33A cervical carcinoma cells which were HPV negative." (PMID 35806128, 2022).
colon carcinoma (6 papers, 2010 to 2024). "We determined the DROSHA rs10719 CC genotype was associated increased risk of colon cancer in subjects 62 years or older (AOR = 3.875; 95% CI, 1.432–10.490) and patients with HTN (AOR, 3.292; 95% CI, 1.362–7.958), DM (AOR = 6.764; 95% CI, 1.424–32.126)." (PMID 26147304, 2015). "Notably, the TCGA data analysis also showed that DROSHA and Ago2 levels are significantly elevated in colon tumors, in addition to the loss of their junctional localization, revealing multiple levels of dysregulation of these proteins correlating with tumor progression." (PMID 32272708, 2020). "In addition, we determined the DROSHA rs10719 CC genotype was associated with increased risk of colon cancer in subjects at 62 years or older (AOR = 3.148; 95% CI, 1.276–7.766; P = 0.013) and subjects younger than 62 years (AOR = 2.940; 95% CI, 1.169–7.399; P = 0.022)." (PMID 26147304, 2015). "Knockdown of DROSHA by siRNA resulted in increased apoptotic responsiveness of colon cancer cells to 5-FU, portending a potential role of the microRNA pathway in Par-4-mediated apoptotic sensitivity." (PMID 20433755, 2010). "That said, whereas the expressions of the majority of appreciably expressed miRNAs in HCT116 colon cancer cells are significantly decreased in individual knockouts (KOs) of DROSHA, DGCR8, XPO5, and DICER, on average, only 3.5% of tsRNA, ysRNA, and rsRNA expressions are impaired." (PMID 39634108, 2024). "Independent analysis of the small RNA transcriptomes of human colon cancer HCT116 WT and DROSHA-KO cells identified 114 miRNAs, 78 ysRNAs, 154 rsRNAs, and 279 tsRNAs to be appreciably expressed (≥ 20 transcripts per million (TPM)) in WT and/or KOs." (PMID 39634108, 2024). "Although little evidence exists that rs17410035 has an impact on DROSHA gene expression or miRNA biogenesis (which could affect gene expression) it has been associated with increased colon cancer (OR = 1.22, p-value = 0.014) and cancer of the head and neck (OR = 2.28, p-value = 0.016)." (PMID 30713548, 2018).
esophageal cancer (6 papers, 2012 to 2023). A primary or metastatic malignant neoplasm involving the esophagus. "It was also shown that overexpression of DROSHA is associated with metastasis and decreased survival in esophageal cancer patients." (PMID 26156018, 2015). "We have found only few papers investigating role of DROSHA rs6877842 SNP in T-cell lymphoma, esophageal cancer, and idiopathic ovarian insufficiency." (PMID 26688807, 2015).
pineoblastoma (5 papers, 2018 to 2025). Pineoblastoma is a rare, malignant type of supratentorial primitive neuroectodermal tumor (sPNET), found mainly in children (less than 10% of cases are reported in adults), and located in the pineal region of the brain but that can metastasize along the neuroaxis. "Here, the authors genomically interrogated pediatric and adult pineoblastomas and found novel variants including recurrent homozygous deletions of DROSHA." (PMID 30030436, 2018). "A somatic LOF variant combined with a germline LOF variant of DROSHA, similarly to the LOH in DICER1 syndrome, leads to pineoblastoma formation." (PMID 40940982, 2025). "In fact, the absence of DICER1 and DROSHA mutations differentiates PPTID from pineoblastoma." (PMID 37444483, 2023). "Moreover, somatic DROSHA and DGCR8 mutations, both related to the Dicer miRNA-regulating pathway, have been recently documented in pineoblastomas, in addition to germline and somatic DICER1 mutations, indicating that pineoblastoma development is influenced by disturbances of miRNA processes." (PMID 33552988, 2020).
viral infections (5 papers, 2015 to 2023). "A dysregulation of the expression of genes involved in miRNA biogenesis had actually been found in several other viral infections: Dengue virus infection led to a decrease of mRNA levels of DICER, DROSHA, AGO1, and AGO2 in Huh-7 cells and this was associated with increased viral replication." (PMID 37243263, 2023).
bladder cancer (4 papers, 2013 to 2023). "The alteration from the T allele to the C allele helps the gene to get rid of miR-27b control, leading to the enhanced expression of the DROSHA enzyme and a significantly increased risk of bladder cancer." (PMID 28187437, 2017). "For instance, a functional SNP (rs10719 T > C) in the 3′ untranslated region (UTR) of DROSHA gene was associated with the risk of bladder cancer by disturbing the binding of hsa-miR-27b and in turn affecting DROSHA expression." (PMID 27270650, 2016). "Genotype frequencies of the DICER and DROSHA SNPs among bladder cancer cases and controls and their association with bladder cancer risk." (PMID 24312312, 2013). "In the present association study, we found that DROSHA 3’UTR rs10719TC polymorphism was associated with the risk of bladder cancer." (PMID 24312312, 2013). "We performed a case-control study of 685 bladder cancer cases and 730 controls to investigate the association between the seven functional SNPs of DICER and DROSHA genes and bladder cancer risk." (PMID 24312312, 2013). "In this study, we found that DROSHA 3’UTR polymorphism rs10719TC can increase the risk of bladder cancer in a Chinese population, which was located near a miRNA binding site." (PMID 24312312, 2013). "Here, we propose that it is warranted to investigate the roles of the DICER and DROSHA in the susceptibility to bladder cancer." (PMID 24312312, 2013). "Accumulated evidences have shown that imbalance DICER and DROSHA expression levels are associated with bladder cancer risk." (PMID 24312312, 2013). "In order to explore the possible mechanism of the DROSHA 3’UTR in the bladder cancer risk, we performed the functional assays." (PMID 24312312, 2013). "In conclusion, we identified the risk allele of rs10719TC located in DROSHA 3’UTR and rs10719 T to C substitution can affect DROSHA protein expression by hsa-miR-27b target, which provided the possible mechanism in bladder cancer risk." (PMID 24312312, 2013). "In the present study, rs10719TC was associated with bladder cancer risk and it was adjacent to the hsa-miR-27a/b binding site in DROSHA 3’UTR." (PMID 24312312, 2013). "We found that rs10719T>C polymorphism located in 3’ untranslated region (UTR) of DROSHA gene was associated with the increased risk of bladder cancer." (PMID 24312312, 2013). "The over-expression of DROSHA is then shown to be associated with poor bladder cancer prognosis." (PMID 28187437, 2017). "Taken together, we hypothesized that the genetic variants of DICER and DROSHA are also be associated with the susceptibility to bladder cancer in a Chinese population." (PMID 24312312, 2013). "On the basis of this postulation, we selected seven polymorphisms of DICER (rs12323635CT, rs13078TA, rs1057035TC, and rs3742330AG) and DROSHA (rs2291109AT, rs10719TC, and rs642321CT) to evaluate the association between the genetic variants of DICER and DROSHA genes and risk of bladder cancer." (PMID 24312312, 2013). "In this study, we hypothesized that genetic variations of the DICER and DROSHA genes were associated with the bladder cancer risk." (PMID 24312312, 2013). "Taken together, these findings suggested that DROSHA rs10719T>C polymorphism may be associated with bladder cancer risk in a Chinese population, and hsa-miR-27b can influence the expression of DROSHA protein by binding with 3’UTR." (PMID 24312312, 2013). "Thus, the C allele is associated with an increased risk of bladder cancer, potentially through increased DROSHA expression, which was consistent with the previous finding." (PMID 24312312, 2013). "Therefore, we hypothesized that DROSHA 3’UTR rs10719C allele can increase the risk of bladder cancer, mainly through regulating the expression of DROSHA." (PMID 24312312, 2013). "Instead, miRNAs are globally dysregulated due to the over-expression of DROSHA protein in bladder cancer." (PMID 28187437, 2017).
bladder cancer (continued). "Catto notes that in comparison with healthy controls, the obvious disorder of miRNA expression in patients with bladder cancer is related to the transcriptionally over-expressed DROSHA in bladder tumour tissues." (PMID 28187437, 2017). "In the present study, hsa-miR-27b was firstly reported to regulate the expression of DROSHA in bladder cancer." (PMID 24312312, 2013). "Previous study had also revealed that over expression of DROSHA can promote cell proliferation and inhibit cell apoptosis in bladder cancer." (PMID 24312312, 2013). "We observed that subjects with the DROSHA 3’UTR rs10719C allele (TC and CC genotypes) had a 1.24-fold increased risk of bladder cancer (Adjusted OR = 1.25, 95% CI = 1.01-1.55, P = 0.041) compared with the rs10719TT genotype." (PMID 24312312, 2013). "This research also illustrates that the high expression of DROSHA in bladder cancer and the variation in miRNA expression may involve feedback loop regulation, and they may cooperatively participate in bladder tumourigenesis." (PMID 28187437, 2017). "Recently, Han and his colleagues also found that DICER and DROSHA expression levels were up-regulated in bladder cancer tissues compared to the matched normal bladder tissues, and silencing DICER or DROSHA can inhibit cell proliferation and induce cell apoptosis." (PMID 24312312, 2013). "Although it is easy to understand that the upregulation of the DROSHA protein can increase the expression of oncogenic miRNAs in bladder cancer, the question as to whether upregulated DROSHA also plays a role in terms of numerous downregulated/silenced miRNAs remains to be answered." (PMID 28187437, 2017).
breast tumor (4 papers, 2012 to 2019). "Our previous work indicated that HA/CD44-activated PKCε promotes Nanog interaction with p68 and DROSHA leading to biosynthetic processing and production of miR-21 in breast tumor cells." (PMID 24606718, 2014). "miR-877 is a DROSHA independent intronic microRNA, up-regulated in our breast tumor samples." (PMID 22438871, 2012). "We found that these genes were deregulated in ER+ compared to ER− breast tumors: DICER1, DROSHA and DGCR8 were significantly under-expressed in ER− while AGO2 was moderate over-expressed in ER−." (PMID 26141719, 2015).
colorectal cancer (4 papers, 2015 to 2024). A primary or metastatic malignant neoplasm that affects the colon or rectum. "To identify the transcription start sites of intergenic miRNAs, we utilized the DROSHA knockout human colorectal cancer cell lines that we established recently." (PMID 27835943, 2016). "To better understand the function of TSS-miRNAs, we applied a modified Crosslinking, Ligation, and Sequencing of Hybrids on Argonaute (AGO-qCLASH) to identify the targets for TSS-miRNAs in HCT116 colorectal cancer cells with or without DROSHA knockout." (PMID 34914716, 2021).
myelodysplastic syndrome (4 papers, 2019 to 2023). A clonal hematopoietic disorder characterized by dysplasia and ineffective hematopoiesis in one or more of the hematopoietic cell lines. "DICER and DROSHA downregulation in mesenchymal stromal cells from myelodysplastic syndrome was associated with a global down expression of microRNAs involved in cell migration and attachment." (PMID 36983035, 2023). "Here, we analyze 3′-UTR variants in DICER1 and DROSHA genes in the context of myelodysplastic syndrome (MDS) development." (PMID 34287278, 2021). "In particular, the downregulated expression of both miRNA processing endonucleases, DICER1 and DROSHA, was demonstrated in MSCs from myelodysplastic syndrome patients compared to normal cells." (PMID 34572006, 2021). "Moreover, further investigations demonstrated the downregulated expression of both miRNA processing endonucleases DICER1 and DROSHA in MSCs from myelodysplastic syndrome patient cells compared to normal cells." (PMID 34287278, 2021).
neuroblastoma (4 papers, 2012 to 2021). Neuroblastoma (NB) is the most common solid, extracranial childhood tumor. "For neuroblastoma, the expression level of DROSHA decreased in advanced-stage patients and was associated with poor prognosis." (PMID 33981333, 2021).
cervical squamous cell carcinoma (3 papers, 2010 to 2015). A squamous cell carcinoma arising from the cervical epithelium. "Our results and the notion about the oncogenic role of DROSHA are very much in line with previous results suggesting that DROSHA is a key gene driving frequent gains of the 5p-arm in cervical squamous cell carcinoma (SCC)." (PMID 26156018, 2015). "Higher expression of DROSHA was found in cervical squamous cell carcinomas and epithelial skin cancers." (PMID 23671264, 2013).
DICER1 syndrome (3 papers, 2015 to 2025). "This is why additional research about DROSHA could aid in revealing pathogenetic mechanisms that may also provide insights into tumorigenesis in DICER1 syndrome." (PMID 40940982, 2025).
endometrial cancer (3 papers, 2012 to 2023). Primary or metastatic malignant neoplasm involving the endometrium (mucous membrane that lines the endometrial cavity). "We recently reported decreased DROSHA protein levels in adenomyosis and suggested a possible relationship between its pathophysiology and endometrial cancer." (PMID 36983035, 2023).
gastric cancer (3 papers, 2017 to 2025). A primary or metastatic malignant neoplasm involving the stomach. "For example, SNVs in DROSHA have been associated with gastric cancer and susceptibility to congenital heart disease, whereas gene variants in DICER1 occur at significantly higher allele frequencies in individuals with endometrial and hepatocellular carcinoma than in the healthy population." (PMID 36968598, 2023). "The present study investigates the influence of genetic variants in miRNA machinery genes (DROSHA, DICER, AGO1, and GEMIN4) on gastric cancer in Chinese Han population, further revealing the genetic mechanisms of gastric cancer occurrence and development." (PMID 29156806, 2017).
non-small cell lung carcinoma (3 papers, 2010 to 2024). A group of at least three distinct histological types of lung cancer, including non-small cell squamous cell carcinoma, adenocarcinoma, and large cell carcinoma. "The combination of two miRNA biogenesis genes (DICER1 and DROSHA) and four miRNAs (miR-30d, miR-21, miR-17, and miR-155) is one of the putative predictive indicators in non-small cell lung cancer." (PMID 39132504, 2024).
Parkinson disease (3 papers, 2017 to 2023). A progressive degenerative disorder of the central nervous system characterized by loss of dopamine producing neurons in the substantia nigra and the presence of Lewy bodies in the substantia nigra and locus coeruleus. "The same group also showed that 6-hydroxydopamine (6-OHDA), a neurotoxin associated with Parkinson’s disease, destabilized DROSHA via p38 MAPK phosphorylation in a mouse model of Parkinson’s disease." (PMID 37099569, 2023). "Indeed DROSHA is involved in the cellular response to DNA damage in neuronal cells carrying a Parkinson’s disease-linked mitochondrial mutation." (PMID 33558311, 2021).
adenoma (2 papers, 2013 to 2021). A neoplasm arising from the epithelium. "Particularly, TARBP2, DICER and DROSHA miRNA-target genes are significantly overexpressed in ACCs when compared with adenomas and normal adrenal tissue samples." (PMID 34829730, 2021). "We show that TARBP2, DICER, and DROSHA are significantly over-expressed in ACC when compared with adenomas and adrenal cortices." (PMID 23671264, 2013). "Our results show a significant over-expression of TARBP2, DICER, and DROSHA in the carcinomas compared with adenomas or adrenal cortices (P<0.001 for all comparisons)." (PMID 23671264, 2013). "Significant over-expression of TARBP2 (1.3- to 4-fold, P<0.0001), DICER (0.4- to 5-fold, P<0.0001), and DROSHA (0.2- to 4.5-fold, P<0.0001) was also observed in carcinomas when compared with adenomas." (PMID 23671264, 2013). "By contrast, abnormal mRNA expression of TARBP2, DICER, and DROSHA was less frequent in adenomas (TARBP2, 32% (14/43); DICER, 37% (16/43); and DROSHA, 40% (17/43))." (PMID 23671264, 2013). "Here, we evaluated the mRNA expression of DROSHA, DGCR8, DICER (DICER1), TARBP2, and PRKRA, the core components in the miRNA biogenesis pathway, in a cohort of 73 adrenocortical tumors (including 43 adenomas and 30 carcinomas) and nine normal adrenal cortices using a RT-qPCR approach." (PMID 23671264, 2013). "Furthermore, we demonstrate that mRNA expression of TARBP2, but not DICER or DROSHA, is a strong molecular predictor to discriminate between adenomas and carcinomas." (PMID 23671264, 2013).
bladder tumor (2 papers, 2013 to 2017). "A total of 61 bladder tumor tissues with different genotypes of the DROSHA rs10719TC polymorphism were used to assess the expression of DROSHA mRNA." (PMID 24312312, 2013). "In bladder tumour tissue specimens from clinical patients, a remarkable increase in expression is observed in both the DROSHA protein and its mRNA." (PMID 28187437, 2017).